IGF1 (insulin like growth factor 1)
Diseases named in the same sentence as IGF1 in open-access papers (continued):
Sharing a sentence is not in itself a finding about the gene and the disease.
acromegaly (continued). "The underlying pathology of acromegaly is based on the stimulation of GH-receptors leading to the production of insulin-like growth factor-1 (IGF-1)." (PMID 39311322, 2024). "Acromegaly is a rare chronic endocrine disorder that develops when the pituitary gland produces excess hGH and consequential IGF-1 during adulthood, leading to multisystem disease associated with increased morbidity and mortality." (PMID 39062037, 2024). "Acromegaly is characterized by increased levels of growth hormone (GH) and insulin-like growth factor-1 (IGF-1) and is caused in the majority of cases by a GH-producing pituitary adenoma." (PMID 39202522, 2024). "Risk factors for primary OA have been reported to also influence risk of acromegalic arthropathy (e.g., age, sex, and BMI), and there are acromegaly-specific risk factors (e.g. baseline IGF-1 levels, and disease duration)." (PMID 39485592, 2024). "Acromegaly is a rare and severe endocrine disorder due to the prolonged exposure to high circulating levels of GH and IGF-1, caused in more than 95% of cases by a GH-secreting pituitary adenoma." (PMID 38967765, 2024). "Consistently, in multivariate analyses, the probability of uncontrolled acromegaly was influenced by baseline IGF-1 value: patients with IGF-1 <300 μg/L had the lowest risk of un-controlled acromegaly (ES = 0.29, 95% CI: 0.23–0.36)." (PMID 38197875, 2024). "Conversely, excessively high IGF-1 levels, as seen in acromegaly, are linked to a higher incidence of HF." (PMID 39544311, 2024). "As common functional PitNETs, somatotroph adenomas arise from PIT1 lineage cells and cause acromegaly due to excessive GH and IGF-1 levels." (PMID 39596626, 2024). "Reduced IGF-1 levels are associated with an increased risk of HF and higher HF-related mortality, while excessively high levels, as seen in acromegaly, are linked to a higher incidence of HF." (PMID 39544311, 2024). "Due to chronic exposure to GH and IGF-1, patients with acromegaly are at a higher risk of CVD, certain neoplasms, obstructive sleep apnea, arthropathy, as well as endocrine and metabolic disorders." (PMID 39337013, 2024). "A definitively elevated IGF-1 level in a patient with symptoms of GH excess is diagnostic of acromegaly." (PMID 36721176, 2023). "Background and Objectives: Acromegaly is a rare disease associated with increased levels of growth hormones (GHs) that stimulates the hepatic production of insulin growth factor-1 (IGF-1)." (PMID 37374352, 2023). "Acromegaly is usually caused by growth hormone (GH)-secreting pituitary adenoma, leading to elevated GH as well as insulin-like growth factor 1 (IGF-1) levels." (PMID 37442901, 2023). "Changes in the musculoskeletal system at acromegaly are associated with the GH and IGF-1 levels, playing a vital role in the regulation of cartilaginous and osseous tissue homeostasis, bone growth in length, and the increase in the mass of osseous tissues." (PMID 37766690, 2023). "Chronic exposure to excessive GH and IGF-1 is likely associated with several systematic comorbidities in acromegaly, including malignant and benign tumors." (PMID 37442901, 2023). "Acromegaly is an uncommon systematic endocrine disease caused by the hypersecretion of human growth hormone and, consequently, of insulin-like growth factor-1 during adulthood." (PMID 37959322, 2023). "Acromegaly is almost caused by growth hormone (GH)-secreting pituitary adenoma and is accompanied by an increase in GH and insulin-like growth factor 1 (IGF-1)." (PMID 37161564, 2023). "Acromegaly is a rare disease, caused by the overproduction of growth hormone (GH), which, consequently, leads to the hypersecretion of insulin-like growth factor-1 (IGF-1)." (PMID 37446150, 2023). "Acromegaly is characterized by the chronic hypersecretion of growth hormone (GH) and insulin-like growth factor 1 (IGF-1), most commonly caused by a pituitary adenoma." (PMID 38137499, 2023).
acromegaly (continued). "The goals of acromegaly therapy, such as neurosurgical treatment and somatostatin analogues are mainly to normalise GH and IGF-1 levels, lower symptoms, reduce the risk of developing comorbidities, and prolong survival." (PMID 36841880, 2023). "Somatotropinomas are the main cause of acromegaly, a chronic progressive disease associated with hypersecretion of growth hormone (GH) and insulin-like growth factor 1 (IGF-1)." (PMID 37766690, 2023). "Increased growth hormone and IGF-1 in acromegaly generally cause changes in body composition with anabolic, lipolytic and sodium retention effects." (PMID 37373801, 2023). "Acromegaly is a chronic systemic disease caused by excess levels of growth hormone (GH) and consequently insulin-like growth factor-1 (IGF-1) that is caused by a GH-secreting pituitary adenoma in the majority of the cases." (PMID 36945936, 2023). "Both gigantism and acromegaly are rare disorders that are caused by excessive secretion of GH and IGF1, and acromegaly occurs when excess GH is present in individuals after epiphyseal closure." (PMID 37476831, 2023). "Acromegaly is usually caused by a pituitary adenoma with persistent growth hormone (GH) hypersecretion and consecutively elevated insulin-like growth factor 1 (IGF-1) levels." (PMID 37665404, 2023). "Acromegaly is a chronic disease caused by the overproduction of growth hormone (GH) and accompanying insulin-like growth factor-1 (IGF-1), which is often caused by GH-secreting pituitary adenomas." (PMID 36983284, 2023). "Acromegaly is a chronic systemic disease caused by an excessive growth hormone (GH) and insulin-like growth factor 1 (IGF-1) secretion, in a substantial majority due to a GH-secreting pituitary adenoma." (PMID 37364152, 2023). "Patients with acromegaly tend to have chronically elevated GH and IGF-1 levels, which cause excessive growth of body tissues characterized by the clinical findings of a prominent forehead, large jaw, large hands and feet, and thickened skin." (PMID 37755395, 2023). "All eight tumours causing acromegaly expressed growth hormone (GH) and produced elevated insulin-like growth factor 1 (IGF-1) levels (mean 3.1× upper limit of normal)." (PMID 37851558, 2023). "Age was the only factor at baseline associated with mortality risk in acromegaly (HR 1.16 (95% CI 1.07–1.26)), whereas sex, IGF-1/ULN levels, tumor size at diagnosis, and first treatment modality (surgery or SSAs) did not influence mortality risk." (PMID 36525222, 2023). "Acromegaly is a disorder caused by chronic growth hormone (GH) hypersecretion leading to IGF-1 over-production." (PMID 36874742, 2023). "Acromegaly is a rare disease, with a reported prevalence of 0.006%, being characterized by growth hormone (GH) and insulin-like-growth factor (IGF-1) excess, caused, in ~99% of cases, by a GH-secreting pituitary adenoma." (PMID 36882643, 2023). "Acromegaly is an uncommon systematic endocrine disease caused by the hypersecretion of human growth hormone (hGH) and, consequently, of insulin-like growth factor-1 (IGF-1) during adulthood with physical changes occurring slowly over several years." (PMID 37959322, 2023). "Here, we summarize the relevant literature concerning cognitive-behavioral research on acromegaly to demonstrate the impact of long-term impairment caused by GH and IGF-1 on the cognitive behavior of patients." (PMID 36983284, 2023). "Acromegaly is a rare systemic disease caused by pathologic secretion of growth hormone (GH) and Insulin-like growth factor (IGF1)." (PMID 36973824, 2023). "It is under development for the treatment of acromegaly, which is caused by excess secretion of growth hormone, which stimulates excess production of insulin-like growth factor 1 (IGF1)." (PMID 37513908, 2023).
acromegaly (continued). "IGF1, as a surrogate marker of active acromegaly and, potentially, the presence of other risk factors (family history of DM or high body mass index), provides special clues for developing cardio-metabolic gestational complications." (PMID 36359512, 2022). "Not only the level of sclerostin values differed significantly across studies when compared between patients in different acromegaly phases and healthy controls, also the direction of associations between sclerostin and GH/IGF-1 levels was highly variable." (PMID 34448099, 2022). "Sensitivity analysis was performed after excluding 40 patients with acromegaly, and the results revealing the relationship between IGF-1 levels and the risk of IVS thickening, which was independent of acromegaly, were stable." (PMID 36568107, 2022). "Treatment of acromegaly is aimed at excising the disease-causing lesion and reducing GH and IGF-1 levels to normal values." (PMID 34498217, 2022). "Acromegaly patients <40 years of age were found to have significantly larger prostate than healthy men (18.2 vs. 28.5 mL, P < 0.001), and suppression of GH and IGF-1 using octreotide caused prostate shrinkage." (PMID 35370981, 2022). "The excess of GH and insulin-like growth factor 1 (IGF-1) results in a disease known as acromegaly, that is associated with increased morbidity and mortality." (PMID 34128215, 2022). "Somatotroph adenomas are a kind of functional pituitary adenomas that cause acromegaly due to the excessive secretion of growth hormone (GH) and insulin-like growth factor (IGF-1)." (PMID 36361871, 2022). "Acromegaly is a rare, progressive disease, caused by an oversecretion of growth hormone (GH) and elevated levels of insulin-like growth factor 1 (IGF-1) in the bloodstream." (PMID 34642894, 2022). "Association between insulin-like growth factor-1 and interventricular septal thickening stratified by sex, age, and acromegaly." (PMID 36568107, 2022). "Acromegaly is characterized by excessive GH and, consequently, IGF-1 and is the most frequent cause of GH-secreting pituitary adenoma." (PMID 35448486, 2022). "Excess GH/IGF-1 in somatotroph adenoma patients causes the overgrowth of some tissues and multiple metabolic abnormalities by affecting body composition, protein dynamics, and molecular mechanisms in adults." (PMID 36361871, 2022). "Acromegaly is a severe and life-threatening disease caused by persistent excess of growth hormone (GH), which stimulates synthesis and secretion of the insulin-like growth factor-1 (IGF-1)." (PMID 36497102, 2022). "We mentioned before that increased phosphorus has been associated with increased GH and IGF-1 in patients with acromegaly." (PMID 35340319, 2022). "Acromegaly is an uncommon chronic disease, caused by excessive production of the growth hormone (GH) and the insulin-like growth factor 1 (IGF-1)." (PMID 35528019, 2022). "Elevated serum concentrations of IGF-1 are broadly accepted as the screening test of choice in the diagnostic workflow of patients with acromegaly." (PMID 36498723, 2022). "Acromegaly and gigantism are conditions caused by elevated circulating growth hormone (GH) and insulin-like growth factor 1 (IGF-1) that manifest as characteristic pathophysiological phenotypes." (PMID 35992136, 2022). "Acromegaly is a rare pathology characterized by chronic hypersecretion of Growth Hormone (GH) and Insulin-like Growth Factor-1 (IGF-1) that causes somatic, metabolic, and systemic changes." (PMID 35364803, 2022). "IGF1 has been reported as a promotor in other endocrine disorders underlying IR, such as acromegaly." (PMID 36292208, 2022). "Although GH and IGF-1 are implicated in carcinogenesis, as supported by epidemiological and experimental data, the increased risk of cancer in acromegaly remains an unclear issue." (PMID 35364803, 2022).
acromegaly (continued). "It has been well established that acromegaly characterized by excess GH and IGF-1 levels causes a systemic involvement with multiple comorbidities and increasing mortality in patients." (PMID 36505847, 2022). "Acromegaly, an endocrine and metabolic disease caused by GHPAs, is partially attributable to an excessive function of the GH and insulin-like growth factor-1 (IGF1) hormones." (PMID 36139495, 2022). "A longer time of exposure to GH and IGF-1 hypersecretion was also associated to skeletal fragility in acromegaly and to an increased risk of VFs." (PMID 35922724, 2022). "Treatment of acromegaly is aimed at resecting the disease-causing lesion and reducing GH and IGF-1 levels to normal values which results in normal-life expectancy and improvement in comorbidities." (PMID 36187106, 2022). "High circulating GH and IGF-1 cause various systemic impacts (cardiovascular disease, hypertension, diabetes, etc.)that cause an increase in all-cause mortality for patients with acromegaly." (PMID 35992136, 2022). "IGF-1 is a potent promoter of CRC, which is consistent with the findings of epidemiological studies wherein patients with acromegaly with high serum level of IGF-1 exhibited greater susceptibility to CRC." (PMID 35296101, 2022). "In the clinical settings of chronic supra-physiological growth hormone and IGF-1 levels in patients with acromegaly, the risk to development of malignancies is still controversial (Loeper & Ezzat 2008, Boguszewski & Ayuk 2016, Boguszewski & Boguszewski 2019)." (PMID 37435457, 2022). "Acromegaly is a chronic endocrine disease most commonly caused by a pituitary adenoma that produces GH (growth hormone), leading to a chronic increase of IGF-1 (Insulin Growth Factor-1)." (PMID 36577870, 2022). "Acromegaly is a rare disease characterized by growth hormone (GH) and insulin-like growth factor type 1 (IGF-1) hypersecretion, and it is usually caused by a GH-producing pituitary adenoma." (PMID 35185796, 2022). "Physiological pregnancies are associated with massive changes of hormone status throughout the three trimesters of gestation, including those already known to underlie different pathogenic loops in acromegaly, such as GH, IGF1, insulin and estrogens." (PMID 36359512, 2022). "Recent studies have shown that strict control of GH and IGF-1 levels has reduced the death risk of acromegaly to a level comparable to that of the general population." (PMID 33869029, 2021). "Higher cancer risk was reported to be associated with acromegaly, which is characterized by increased growth hormone levels with concomitant elevated levels of IGF1." (PMID 34858769, 2021). "A link was also investigated between acromegaly, increased levels of GH/IGF-1 and higher risk of colorectal neoplasia." (PMID 34208601, 2021). "Acromegaly is a rare disease caused by the hypersecretion of growth hormone (GH) and a secondary insulin‐like factor 1 (IGF‐1) secretion, in most cases, due to a secreting presence of pituitary adenoma." (PMID 33855226, 2021). "When growth hormone (GH) secretion is high, it stimulates the hepatic secretion of insulin-like growth factor-1 (IGF-1), which causes the majority of acromegaly clinical symptoms." (PMID 34530525, 2021). "Lowering the IGF-1 levels is a crucial objective in the management of patients with persistent acromegaly, as higher values are linked with higher mortality." (PMID 33572555, 2021). "Acromegaly is a slowly progressive disease caused by persistent excess of circulating growth hormone (GH) and insulin-like growth factor-1 (IGF-1)." (PMID 33803429, 2021). "Acromegaly is a rare disease caused by high serum levels of growth hormone (GH) and insulin-like growth factor 1 (IGF-1), often originating from a pituitary adenoma." (PMID 33853563, 2021). "Acromegaly develops as a result of excessive growth hormone (GH) and insulin-like growth factor-1 (IGF-1) release and is caused mostly by a pituitary adenoma." (PMID 34217172, 2021).
acromegaly (continued). "Considering GH and IGF‐1 cut‐off values to define cured, active, or discordant acromegaly, only cured acromegaly was associated with global AcroQoL scores (p = 0.05)." (PMID 33855226, 2021). "Acromegaly (AG) is a rare disease caused by excessive production of the growth hormone (GH) and insulin-like growth factor 1 (IGF1)." (PMID 35211089, 2021). "Gigantism and acromegaly are both rare disorders caused by excess GH and IGF-1 secretions; however, gigantism occurs when GH excess triggers linear development prior to puberty, whereas acromegaly occurs after epiphyseal closure." (PMID 33849304, 2021). "Acromegaly is a rare disease caused by high serum levels of growth hormone (GH) and insulin-like growth factor 1 (IGF-1) usually from a pituitary adenoma." (PMID 33853563, 2021). "Acromegaly is a rare disease characterized by excessive GH and insulin-like growth factor 1 (IGF-1), caused mainly by GH-producing pituitary adenoma." (PMID 34245432, 2021). "Acromegaly is a rare chronic condition caused by the excessive secretion of Growth Hormone (GH) and Insulin-like Growth Factor 1 (IGF-1)." (PMID 34744996, 2021). "The study revealed that high IGF-1 levels are significantly related to the formation of colonic polyps, indicating that acromegaly patients are at a high risk of acquiring colonic polyps." (PMID 34987906, 2021). "Acromegaly is a rare, chronic disease characterized by increased growth hormone (GH) and insulin-like growth factor 1 (IGF-1) levels, mostly caused by GH secreting pituitary adenoma." (PMID 33389987, 2021). "Acromegaly is characterized by elevated growth hormone (GH) and insulin-like growth factor-1 (IGF-1), most commonly caused by pituitary adenoma." (PMID 34603213, 2021). "Acromegaly is a disease characterized by an increase in insulin-like growth factor 1 (IGF-1) and growth hormone (GH), and it is usually caused by a pituitary adenoma." (PMID 35059575, 2021). "A positive association between IGF-1 and OA risk is further supported by findings from individuals with acromegaly (a disorder of excess growth hormone production), who have increased OA risk." (PMID 33027520, 2021). "The most common change caused by acromegaly, depending on IGF-1 level, is microvascular wall hypertrophy." (PMID 35059575, 2021). "Acromegaly is a disease of excess growth hormone (GH) and insulin-like growth factor-1 (IGF-1) levels, with GH-secreting pituitary adenomas causing 98% of cases." (PMID 34867787, 2021). "Acromegaly is a rare disease caused by overproduction of growth hormone (GH) by a pituitary adenoma, and consequently increased insulin-like growth factor 1 (IGF-1) concentration." (PMID 34501445, 2021). "Treatment goals for GH-secreting PA include: (i) normalization of GH and IGF-1 levels; (ii) reduction of tumor size; and (iii) reduction of acromegaly-associated comorbidities." (PMID 33946142, 2021). "Acromegaly is a chronic disorder resulting from excessive secretion of growth hormone and (GH) and insulin-like growth factor 1 (IGF-1) and is associated with several comorbidities." (PMID 34912391, 2021). "Mortality rates are 2 to 2.5 times higher in patients with acromegaly, and with normalization of GH and IGF-1 levels, the mortality risk is similar to the general population." (PMID 34745010, 2021). "With an incidence between 0.2 and 1.1 per 100,000 and year, acromegaly is a rare endocrinological disorder mostly caused by growth hormone (GH)-secreting adenomas of the pituitary gland, which lead to elevated insulin-like growth factor 1 (IGF-1) levels." (PMID 33572555, 2021). "This review discusses the prevalence of discordant GH and IGF-1 outcomes in patients with acromegaly; factors causing this discrepancy; the impact of hormone levels on treatment outcomes." (PMID 35262296, 2021). "Acromegaly is a chronic neuroendocrine disease that is usually caused by pituitary adenoma and characterized by elevated growth hormone (GH) and insulin-like growth factor 1 (IGF-1) levels in serum." (PMID 32148485, 2020).